H3C4 (H3 clustered histone 4)
Description:
Core component of nucleosome. Nucleosomes wrap and compact DNA into chromatin, limiting DNA accessibility to the cellular machineries which require DNA as a template. Histones thereby play a central role in transcription regulation, DNA repair, DNA replication and chromosomal stability. DNA accessibility is regulated via a complex set of post-translational modifications of histones, also called histone code, and nucleosome remodeling.
Synonyms: H3FB; HIST1H3D; H3/b
Gene: Protein-coding gene on chromosome 6 (26,195,164 to 26,197,286, reverse strand). Ensembl gene ENSG00000197409.
Subcellular location: Nucleus; Chromosome
Subcellular location (Human Protein Atlas): Nucleoplasm
Pathways (Reactome):
Gene expression (Transcription): B-WICH complex positively regulates rRNA expression; DNA methylation; ERCC6 (CSB) and EHMT2 (G9a) positively regulate rRNA expression; MLL4 and MLL3 complexes regulate expression of PPARG target genes in adipogenesis and hepatic steatosis; NoRC negatively regulates rRNA expression; PRC2 methylates histones and DNA; RNA Polymerase I Promoter Escape; RNA Polymerase I Promoter Opening; RUNX1 regulates genes involved in megakaryocyte differentiation and platelet function; RUNX1 regulates transcription of genes involved in differentiation of HSCs; Regulation of endogenous retroelements by KRAB-ZFP proteins; Regulation of endogenous retroelements by Piwi-interacting RNAs (piRNAs); Regulation of endogenous retroelements by the Human Silencing Hub (HUSH) complex; SIRT1 negatively regulates rRNA expression; Transcriptional regulation by small RNAs
Chromatin organization: CHD1 and CHD2 subfamily; CHD6, CHD7, CHD8, CHD9 subfamily; ChAHP complex assembly; Chromatin modifying enzymes; HATs acetylate histones; HDACs deacetylate histones; HDMs demethylate histones; Interaction of NuRD complexes with transcription factors; NuRD complex assembly; PKMTs methylate histone lysines; RMTs methylate histone arginines
Disease: Defective pyroptosis; Dengue Virus-Host Interactions; HCMV Early Events; HCMV Late Events
Signal Transduction: Activated PKN1 stimulates transcription of AR (androgen receptor) regulated genes KLK2 and KLK3; Estrogen-dependent gene expression; Formation of the beta-catenin:TCF transactivating complex; Pre-NOTCH Transcription and Translation
Developmental Biology: Activation of anterior HOX genes in hindbrain development during early embryogenesis; Chromatin modifications during the maternal to zygotic transition (MZT); Transcriptional regulation of granulopoiesis
Immune System: FXIIa activates plasma kallikrein-kinin system; Interleukin-7 signaling; Regulation of PD-L1(CD274) transcription
and 8 more pathways
Gene Ontology:
Molecular function: cadherin binding; protein binding; structural constituent of chromatin; nucleosomal DNA binding; DNA binding; protein heterodimerization activity
Biological process: epigenetic regulation of gene expression; nucleosome assembly; chromatin organization; heterochromatin formation; telomere organization
Cellular component: chromatin; extracellular exosome; membrane; nucleoplasm; nucleosome; nucleus; protein-containing complex; extracellular region; chromosome
Genetic constraint (gnomAD): Loss-of-function variants: 11 observed, 9.72 expected, observed/expected ratio (o/e) 1.13, 90% interval 0.71 to 1.77. That is too few expected variants to judge how well the gene tolerates losing a copy. Missense variants: 216 observed, 207.5 expected, observed/expected ratio (o/e) 1.04, 90% interval 0.93 to 1.16. Synonymous variants: 141 observed, 82.93 expected, observed/expected ratio (o/e) 1.7, 90% interval 1.48 to 1.92.
Homologues: Orthologues: Drosophila melanogaster His3:CG33812 (99% identical), zebrafish si:ch1073-153i20.2 (99% identical), zebrafish si:ch211-113a14.20 (99% identical), zebrafish si:ch211-113a14.23 (99% identical), zebrafish si:ch211-113a14.27 (99% identical), zebrafish zgc:173552 (99% identical), Caenorhabditis elegans his-17 (97% identical), Caenorhabditis elegans his-2 (97% identical), Caenorhabditis elegans his-32 (97% identical), Caenorhabditis elegans his-40 (97% identical), Caenorhabditis elegans his-42 (97% identical), Caenorhabditis elegans his-45 (97% identical), and 5 more. Paralogues in human: H3C1 (100% identical), H3C10 (100% identical), H3C11 (100% identical), H3C12 (100% identical), H3C2 (100% identical), H3C3 (100% identical), H3C6 (100% identical), H3C7 (100% identical), H3C8 (100% identical), H3C13 (99% identical), H3C14 (99% identical), H3C15 (99% identical), and 8 more.
Diseases named in the same sentence as H3C4 in open-access papers:
H3C4 is named in the same sentence as 1 disease in open-access papers, as found by Europe PMC text mining. Sharing a sentence is not in itself a finding about the gene and the disease.
H3C4 shares sentences with these, for which no sentence is quoted: cancer (1 paper).